BPESC1 (blepharophimosis, epicanthus inversus and ptosis candidate 1)
Synonyms: NCRNA00187
Gene: Long non-coding RNA gene on chromosome 3 (139,104,185 to 139,125,171, forward strand). Ensembl gene ENSG00000232416.
Diseases named in the same sentence as BPESC1 in open-access papers:
BPESC1 is named in the same sentence as 1 disease in open-access papers, as found by Europe PMC text mining. Sharing a sentence is not in itself a finding about the gene and the disease. The quoted sentences say what the papers report.
tumor (1 paper, 2020). "Although there is currently no direct evidence of their involvement in tumor development, we found that BPESC1, AC061975.6, and AC079341.1 were associated with the prognosis of patients with stage I HCC." (PMID 32104698, 2020).